VASP (vasodilator stimulated phosphoprotein)
Diseases named in the same sentence as VASP in open-access papers (continued):
Sharing a sentence is not in itself a finding about the gene and the disease.
tumor (continued). "Further studies are required to clarify whether VASP is an important biomarker for early tumor diagnosis and as a therapeutic target." (PMID 37962042, 2023). "When VASP is inhibited, the invasive ability of tumor cells is significantly reduced." (PMID 37962042, 2023). "Moreover, we found that the levels of circRFX3, VASP mRNA and VASP protein were decreased and the levels of miR-1179 and miR-1229 were increased in the xenograft tumor tissues harvested from sh-circRFX3#1 group compared to control group." (PMID 34727925, 2021). "VASP is involved in tumor invasion and/or metastasis progression." (PMID 31886120, 2019). "We speculate that the decreased expression of VASP reduced the adhesion and aggregation of tumor cells, which may lead to the invasion and metastasis of tumor cells into their surroundings." (PMID 31886120, 2019). "Based on these results, it could be concluded that icariin inhibit the tumor cell invasion and migration through the Rac1-dependent VASP pathway." (PMID 27649234, 2016). "However, in cell culture experiments homozygous knockout of VASP suggested rather an inhibitory role for VASP on soft agar colony and tumor formation." (PMID 26336132, 2015). "Another issue is that VASP can be phosphorylated at multiple sites, and depending on its phosphorylation status, may act as a promoter or inhibitor of tumor progression." (PMID 26336132, 2015). "A caveat of “only” looking at expression levels is that VASP can be phosphorylated at multiple sites with different outcome, and dependent on its phosphorylation pattern, VASP may act as a promoter or inhibitor of tumor progression." (PMID 26336132, 2015). "Interestingly, we also noted phosphorylation of proteins associated with cell adhesion and migration, such as VASP and TLN1, which may facilitate interactions with the supportive tumor microenvironment." (PMID 40129242, 2025). "However, current research on VASP involves many deficiencies, such as the lack of research on the specific mechanism by which VASP affects the invasion and migration of some tumor cells, and the lack of survival analysis data of some clinical samples." (PMID 37962042, 2023). "Our study also introduces a RS that integrates patient demographics, tumour characteristics, and key gene expressions such as FN1, VASP, and CEP63 to predict tumour relapse in MIBC patients undergoing NAC." (PMID 40149716, 2025). "As the specific molecular mechanisms of VASP and LC and the regulation of proliferation, migration, invasion, and apoptosis of LC cells have not been thoroughly studied, it cannot be conclusively stated whether VASP can be applied in clinical treatment or used as a new tumor marker." (PMID 37962042, 2023). "miR-4455 functions as a tumor suppressor in GC by targeting VASP, leading to the activation of the PI3K/AKT signaling pathway and inhibition of VASP-mediated proliferation, migration, and invasion of GC cells." (PMID 32218690, 2020). "Icariin was also reported to significantly inhibit tumor cells migration and invasion of human gastric adenocarcinoma cell line BGC-823 via the down-regulation of Rac1 and VASP." (PMID 27649234, 2016). "Furthermore, Cox’s regression analysis showed that FN1, VASP, and CEP63 were independent prognostic factors of tumour relapse." (PMID 40149716, 2025). "In follow-up studies, more attention should be paid to tumor regions where the role of VASP has not been explained in detail and more clinical samples should be collected to analyze the impact of different VASP expression levels on patient prognosis." (PMID 37962042, 2023). "In the control group of MDA-MB-231 tumors, we found tumor metastasis in the lungs of nude mice, which showed green fluorescence, but no metastases were found in the VASP knockdown group." (PMID 31754343, 2019). "Since tumor microenvironmental LPA or S1P activates GPCRs-RhoA-YAP1/TAZ signaling to promote tumorigenesis, we hypothesized that VASP may play a role in GPCR-signaling in GI cancer cells." (PMID 29872721, 2018).
tumor (continued). "ADT-094 increased levels of phospho-Ser239 VASP in HCT116 colon tumor cells without affecting total VASP levels." (PMID 26299804, 2015). "The lack of correspondence between exosomes and tumor tissues for VASP, LGALS3BP, MYH9 and LTBP1 could be due to the fact that these vesicles are loaded through active mechanisms." (PMID 37947594, 2023). "However, VASP has not been studied in some tumor types, and strengthening research on other tumors may provide new ideas for tumor development." (PMID 37962042, 2023). "While VASP and RAPH1 expression did not significantly differ between non-tumor and tumor tissue, CRK and CRKL exhibited an opposite expression pattern." (PMID 39126118, 2024).
infection (4 papers, 2016 to 2025). The state of being infected such as from the introduction of a foreign agent such as serum, vaccine, antigenic substance or organism. "In an intestinal epithelial cell monolayer model of infection, N-WASP, VASP, and Arp2/3 have all been localized to the site of infection." (PMID 40743117, 2025). "Considering an important role in cell survival, we anticipate PKACα is critical for PKA pro-survival signaling and VASP phosphorylation during infection." (PMID 27711191, 2016). "Our findings indicate VASP is phosphorylated by PKA during infection in a T4SS-dependent fashion, and VASP activity is required for PV formation and C. burnetii replication in human macrophages." (PMID 27711191, 2016). "During infection, VASP phosphorylated at S239 may localize to specific regions around the PV where controlled actin depolymerization could occur to provide space for vacuole expansion." (PMID 27711191, 2016). "Therefore, we predicted the kinetics of VASP phosphorylation may differ during early and late stages of infection." (PMID 27711191, 2016). "On day 6 after the infection, we found that the number of EVL/VASP dKO OT-I T cells in the spleen was significantly reduced compared to their WT counterparts (2.6-fold average reduction compared to WT)." (PMID 35757762, 2022). "After ≥8 weeks, we isolated peripheral EVL/VASP dKO and WT OT-I T cells from the LNs and spleen of bone marrow chimeras and adoptively co-transferred them into WT recipient mice for LM-OVA infection." (PMID 35757762, 2022). "Characterization of VASP function in PV formation and identification of additional PKA substrates that promote infection will provide new insight into host-pathogen interactions during Q fever." (PMID 27711191, 2016). "Treatment with H89 significantly reduced VASP phosphorylation, confirming VASP is a downstream target of PKA during infection." (PMID 27711191, 2016). "The abundance of total VASP was not altered during infection or any inhibitor treatment." (PMID 27711191, 2016).
inflammation (1 paper, 2014). Aberrant reaction of the microcirculation characterized by movement of fluid and leukocytes from the blood into extravascular tissues. "Taken together, our data demonstrate that HIF-1α acts downstream of TNF-α to inhibit VASP expression and to modulate the acute pulmonary inflammation process, and these molecules play an important role in the impairment of the alveolar-capillary barrier." (PMID 25051011, 2014). "Taken together, our data demonstrate that VASP, which is negatively regulated by TNF-α, induces HIF-1α activation during the acute pulmonary inflammation process and plays an important role in the impairment of the alveolar-capillary barrier." (PMID 25051011, 2014).
VASP also shares sentences with these, for which no sentence is quoted: breast tumor (2 papers); cardiovascular disease (2); acute lung injury (1); Albright hereditary osteodystrophy (1); anemia (1); Arterial thrombosis (1); atrial fibrillation (1); breast invasive carcinoma (1); cardiac hypertrophy (1); carotid artery thrombosis (1); cervical cancer (1); chronic kidney disease (1); colon (1); colorectal adenocarcinoma (1); COVID-19 (1); hematological disorders (1); HIV-1 infection (1); hyperuricemia (1); leukemia (1); metabolic syndrome (1); metastasis (1); minimal change disease (1); neuroblastoma (1); neurological diseases (1); osteosarcoma (1); overnutrition (1); pancreatic ductal adenocarcinoma (1); renal cell carcinoma (1); Sepsis (1); Tetralogy of Fallot (1).
A further 4 diseases each share a sentence with VASP in 1 paper.